GDF15 (growth differentiation factor 15)
Diseases named in the same sentence as GDF15 in open-access papers (continued):
Sharing a sentence is not in itself a finding about the gene and the disease.
Cachexia (continued). "What’s more, anti-growth differentiation factor 15 (GDF-15) combined with anti-PD-1 therapy enhanced anti-PD-1 efficacy, as GDF-15 is closely tied to cachexia." (PMID 39253074, 2024). "When GDF-15 levels are neutralized in a cancerous mouse model, it is shown to restore muscle mass and muscle function lost during cachexia." (PMID 39394174, 2024). "In conclusion, elevated serum GDF-15 levels were identified as a significant predictor of shorter PFS and OS and an increased risk of cachexia in patients receiving immunotherapy for advanced cancers." (PMID 39766045, 2024). "Other precise biological functions of GDF15 are still poorly defined, but it has been shown that it acts centrally to control appetite and is involved in energy metabolism, with catabolic and cachexia-promoting effects." (PMID 38808117, 2024). "Because of importance of GDF-15 in cancer induced cachexia, we measured its expression in tumor bearing and tumor free mice." (PMID 39394174, 2024). "Approximately 168 adults with non‐small‐cell lung, pancreatic or colorectal cancers who have cachexia and elevated GDF‐15 concentrations will be randomized in a double‐blind, placebo‐controlled study (NCT05546476)." (PMID 38500292, 2024). "GDF15 has been proposed to contribute to anorexia, cachexia, and body weight control via its interactions with these receptors." (PMID 37093513, 2024). "GDF15 is considered one of the important biomarkers of cachexia, playing a crucial role in the pathogenesis of cachexia." (PMID 39172988, 2024). "GDF-15 is involved in energy homeostasis and body weight regulation and plays a distinct role in cachexia." (PMID 39780955, 2024). "Circulating high levels of the cell stress cytokine growth differentiation factor 15 (GDF15, also called MIC-1 and NAG-1) are linked to reduced appetite and food intake, loss of body weight and cancer-associated anorexia-cachexia." (PMID 38474863, 2024). "This pilot study is an important first step toward evaluating the role of GDF15 in childhood cancer cachexia and its potential as a cachexia therapeutic target." (PMID 38146512, 2023). "The interplay of GDF11 and GDF15 in cachexia and the potential effects of GDF11 induction by BET inhibition in that context still remain to be further elucidated." (PMID 37495707, 2023). "Particularly noteworthy were the significant elevations in serum activin A and GDF-15—amounting to 76-fold and 10-fold increase, respectively—relative to baseline values as cancer-induced cachexia progressed." (PMID 37755304, 2023). "Host cells are known to contribute to elevated GDF15 levels in cachexia patients when exposed to drug toxicity." (PMID 37495707, 2023). "GDF15 increases nausea, vomiting, and anorexia in cancer and contributes to malnutrition, with the potential to be a cachexia therapeutic target." (PMID 38146512, 2023). "In NCInu/nu-mice, MC38 cells expressing transgenic human GDF-15 (MC38tghGDF-15 cells) induced cachexia and grew more slowly than control-transfected MC38blank cells." (PMID 37474523, 2023). "The involvement of GDF15 in regulating features of cachexia such as anorexia, body weight and muscle mass is evident and therapeutic development based on this mechanism remains ongoing." (PMID 36642986, 2023). "Although GDF15 overexpression has been identified as an etiological key driver of cachexia, little efforts have been made yet to characterize the molecular basis of GDF15 induction and suppression by drugs." (PMID 37495707, 2023). "It thus remains to be determined how and under which conditions GDF-15 induces cachexia, immune tolerance, or both." (PMID 37474523, 2023). "GDF15 induces weight loss by suppressing appetite, so neutralizing the antibodies against GDF15 reduces cancer‐induced cachexia in mice." (PMID 36444166, 2022). "Serum levels of two cachexia biomarkers, activin A and GDF15, increased significantly during cachexia progression (76‐folds and 10‐folds, respectively)." (PMID 35044098, 2022).
Cachexia (continued). "Future studies will be needed to determine if GDF15 neutralization is efficacious in reversing MCT-induced cachexia and improving physical performance and survival." (PMID 35406637, 2022). "Remarkably, treatment of Adh5−/−Csbm/m mice with an anti‐GDF15 antibody completely prevented DNA damage/GDF15‐ induced cachexia." (PMID 35834102, 2022). "To examine if GDF15 plays a role in cardiac cachexia preclinically, we determined the effect of GDF15 neutralization on the development of cachexia in MCT-induced PAH and cardiac cachexia rat model." (PMID 35406637, 2022). "To investigate if GDF15 is causal in driving cachexia in this model, we first determined the effect of MCT on circulating GDF15 and body weight." (PMID 35406637, 2022). "In patients with cancer cachexia, the level of circulating GDF15 increases in the early stage of cachexia and continues to rise with the progression of cachexia." (PMID 36105371, 2022). "This breakthrough study showed that inhibition of the GDF15-GFRAL pathway is a novel strategy for the treatment of cachexia in a mouse model, and this approach is currently being evaluated in phase I clinical trials." (PMID 35388147, 2022). "Concomitant with elevation of GDF15, the rats dosed with MCT developed cachexia, demonstrated by reduced food intake and loss of body weight, fat, and lean mass, as well as muscle atrophy." (PMID 35406637, 2022). "GDF15 antibody therapy with PF-06946860 is currently being tested in a Phase 1 clinical trial for relieving cachexia–anorexia symptoms in advanced cancer patients." (PMID 36078078, 2022). "Here, we examined the relationship of GDF15 with the development of cachexia in the monocrotaline (MCT)-induced cardiac cachexia rat model." (PMID 35406637, 2022). "The data demonstrate that GDF15 is essential in mediating MCT-induced anorexia and weight loss in vivo and is causal to the development of cachexia in this model." (PMID 35406637, 2022). "In other cachexia models, GDF-15 is capable of inducing anorexia through the activation of GFRAL in the brainstem." (PMID 35941104, 2022). "Since GDF15 appears to influence multiple aspects of CNS-mediated cachexia, including appetite, autonomic outflow and subsequent fat mass wasting, blocking GDF15 signaling represents a promising anti-cachexia strategy." (PMID 34439145, 2021). "Growth differentiation factor-15 (GDF-15) plays an important role in the pathophysiology of cachexia." (PMID 33445790, 2021). "In conclusion, APC patients with high serum GDF-15 showed worsened performance status, anorexia and elevations of inflammation and tumor burden as signatures of cachexia, as well as activation of Akt and JNK in tumor GDF-15-producing pathways." (PMID 34638326, 2021). "We aimed to evaluate the association of circulating growth differentiation factor 15 (GDF-15) with cachexia symptoms and the biological activity of advanced pancreatic cancer (APC)." (PMID 34638326, 2021). "Since GDF15 is known to be upregulated in numerous rodent cachexia models and humans with cancer, it is likely that GDF15-driven SNS engagement mediates wasting during cancer cachexia as a recent report suggests." (PMID 34439145, 2021). "We observed an age-dependent increase in circulating GDF15 levels but no alterations to Gdf15 expression in skeletal muscle, indicating that other sources of GDF15 are more important in regulating circulating GDF15 in cachexia in our models." (PMID 35008253, 2021). "Treatment with GDF15-blocking antibody was capable of preventing cachexia in seven separate xenograft models of cachexia." (PMID 32310257, 2020). "In a subsequent study, the neurons responsible for GDF-15 dependent induction of anorexia and cachexia were localized to the area postrema and the nucleus of the solitary tract." (PMID 32508832, 2020).
Cachexia (continued). "Circulating GDF15 levels are elevated in a range of human disease states, including various forms of cachexia, and GDF15-GFRAL antagonism is emerging as a therapeutic strategy for anorexia/cachexia syndromes." (PMID 32310257, 2020). "From a translational perspective, our findings support a role of GDF15 antagonists for treatment of drug‐induced cachexia." (PMID 30782979, 2019). "When MIC-1/GDF15 is markedly overproduced, such as in advanced cancer, it leads to an anorexia/cachexia syndrome by acting on brain feeding centers in the hypothalamus and hindbrain." (PMID 28081177, 2017). "The TGF-b superfamily cytokine MIC-1/GDF15 circulates in all humans and when overproduced in cancer leads to anorexia/cachexia, by direct action on brain feeding centres." (PMID 23468844, 2013). "MIC-1/GDF15 was first identified as an appetite regulator when it was discovered that its overexpression in cancer and other diseases lead to anorexia/cachexia." (PMID 23468844, 2013). "GDF15 is potentially suggestive of general condition deterioration from aging, organ dysfunction, and decreased muscle mass, which may lead to cachexia in patients with EC." (PMID 41016991, 2026). "However, after dichotomizing these analytes via a median split and controlling for BMI, R&E, stage, cachexia status, sex, and age at diagnosis, a modified model including GDF-15, IL-6 and stage as significant predictors of survival was reached." (PMID 39989973, 2025). "A newly published Phase 2 trial of ponsegromab, a GDF‐15 inhibitor, implements this approach by showing improvement in digital measures of daily physical activity in cancer cachexia patients, as well as increases in weight gain, appetite and skeletal muscle mass." (PMID 40726355, 2025). "As GDF-15-mediated cachexia may independently suppress tumour immunity or diminish immunotherapy efficacy, these findings warrant evaluation to determine whether GDF-15 inhibition can enhance ICI efficacy across or within selected tumour types." (PMID 41294666, 2025). "In this context, targeting GDF15 has emerged as a promising strategy that may help overcome some of the limitations faced by previous cachexia interventions and address both metabolic dysfunction and treatment resistance." (PMID 40868185, 2025). "Indeed, GDF-15 remains significantly increased over all four cachexia stages using ordinal regression even when adjusting for race and ethnicity, stage, age at diagnosis and BMI (P<0.001)." (PMID 39989973, 2025). "Importantly, GDF-15 was one of only two markers which was predictive of “pre-cachexia” status and this molecule predicted survival independently of weight loss based on both a Kaplan Meier estimate and CPE analysis." (PMID 39989973, 2025). "GDF15 primarily drives cachexia by inducing anorexia, leading to reduced nutritional intake." (PMID 40837873, 2025). "In mouse models of cancer cachexia, the antibody-mediated inhibition of GDF15-GFRAL has been shown in distinct studies to reverse the loss of adipose and muscle mass of tumor-bearing subjects, to improve muscle function and physical performance, and to reduce chemotherapy-induced weight loss." (PMID 40868185, 2025). "Since GDF15 has been shown to perform a number of diverse functions in addition to regulating food intake, this cytokine was likely to be involved in aspects other than anorexia during pre-cachexia." (PMID 40124481, 2025). "Importantly, increased circulating levels of IL-6 and GDF15 were observed even before any reduction in food intake, body weight, or muscle mass, and these levels were further elevated at the onset of anorexia-cachexia." (PMID 40124481, 2025). "Pre-cachexia stage can be differentiated by GDF-15 and TIMP-1 levels." (PMID 39989973, 2025).
Cachexia (continued). "Given the significant role of GDF15 in driving muscle wasting and physical activities in cancer cachexia, coupled with the marked increase of circulating levels of GDF15 in PMM patients, it is plausible GDF15 plays a role in mediating the pathways implicated in PMM." (PMID 39976232, 2025). "Hence, this work represents the first time that GDF-15 has been studied in the context of a response to metabolic stress (cachexia) and race." (PMID 39989973, 2025). "Moreover, inactivation of GDF15 signaling in a mouse model of cancer-induced cachexia led to improved muscle mass and physical performance." (PMID 38808117, 2024). "Given the increased GDF15 in irradiated Ppp1r15aΔC/ΔC mice, we hypothesized that the cachexia was mediated by reduced food intake via GDF15 signalling." (PMID 39312445, 2024). "Preclinical and preliminary phase 1 data suggest that ponsegromab‐mediated inactivation of circulating GDF‐15 may lead to improvement in key characteristics of cachexia." (PMID 38500292, 2024). "More in-depth analyses may reveal the relationships between changes in GDF15 levels and changes in parameters of cachexia and heart remodelling." (PMID 39312445, 2024). "The GDF15 targeting agent, ponsegromab, is currently being evaluated in a phase 2 clinical trial of cancer patients with cachexia and elevated GDF15 (NCT05546476) and a separate agent CTL-002 is being tested in combination with ICIs in patients with advanced cancer (NCT04725474)." (PMID 37813923, 2023). "A tool to predict whether a patient will react to a particular anticancer drug with GDF15 overexpression could help reduce risks for chemotherapy-driven development of cachexia." (PMID 37495707, 2023). "Thus GDF-15, beside its known role in cancer-related anorexia and cachexia, emerges as a regulator of T cell extravasation into the tumor microenvironment, which provides an even stronger rationale for therapeutic anti-GDF-15 antibody development." (PMID 37474523, 2023). "Still, limited evidence regarding the role of GDF15 in PC-related cachexia exists." (PMID 36230682, 2022). "The expression of GDF15 is upregulated in many rodent cachexia models and patients with cancer." (PMID 36105371, 2022). "Growth differentiation factor-15 (GDF-15), a member of the transforming growth factor β (TGF-β) superfamily, has been implicated as a biomarker of aging, sarcopenia, muscle wasting, cachexia, mitochondrial disease, decreased physical activity, and energy imbalance." (PMID 36325442, 2022). "We used this cardiac cachexia rat model to investigate the role of GDF15 in MCT-induced cachexia." (PMID 35406637, 2022). "While GDF-15 has antihypertrophic effects on cardiac remodeling and counter-regulates inflammation, studies have shown that chronic elevation of GDF-15 can result in anorexia, inhibition of muscle growth, weight loss, and cachexia." (PMID 35883490, 2022). "GDF15 mAb2 is efficacious in mitigating MCT-induced cachexia in vivo." (PMID 35406637, 2022). "GDF15 was also found to be elevated in CHF and PAH patients; however, it is unknown if GDF15 is causal to the development of cachexia in these patients." (PMID 35406637, 2022). "Our data suggest that GDF15 plays a role in cardiac cachexia, and GDF15 neutralization could potentially be an effective therapeutic approach for the treatment of cachexia in HF or other chronic diseases with elevated GDF15, such as COPD, CKD, and cancer." (PMID 35406637, 2022). "GDF15 could acts as a critical mediator of anorexia-cachexia through the GDF15-mediated activation of hindbrain GFRAL-RET receptors." (PMID 35379793, 2022). "Although the mechanism of GDF15‐induced muscle wasting and lipolysis of cachexia is unclear, circulating GDF15 levels may be the biomarkers of cancer cachexia." (PMID 36105371, 2022). "The increase in GDF15 upon cachexia was much more evident in BALB/c compared to C57BL/6 mice." (PMID 35008253, 2021).
Cachexia (continued). "Indeed, the ability of GDF15 to drive autonomic activation and adipose tissue wasting was only recently described, making it a promising target for alleviating cachexia symptoms through multiple means." (PMID 34439145, 2021). "This clinical trial of CTL-002 is expected to clarify the relationship between GDF-15 and cachexia." (PMID 34638326, 2021). "Nevertheless, its predictive value, in combination with other markers such as albumin, CRP, GDF‐15, or IL‐6, for instance, may represent an efficient signature for diagnosis of cachexia." (PMID 34427055, 2021). "Many cachexia-inducing factors such as activin A (ActA), myostatin (Mstn), and growth/differentiation factor 15 (GDF15) are members of the transforming growth factor (TGF)-β family, capable of inducing muscle wasting and fat loss in preclinical cancer cachexia models." (PMID 33925872, 2021). "Importantly, elevation of GDF15 suppresses appetite via activation of hypothalamic neurons, and the cachexia-inducing properties GDF15 are thought to be a result of anorexia." (PMID 33329046, 2020). "As such, muscle derived GDF15 was reported to stimulate lipolysis in adipocytes, which in the context of cachexia could contribute to adipose tissue depletion." (PMID 33329046, 2020). "The hypothesis that GDF15 may play detrimental role is also supported by many studies on the effects of GDF15 on cachexia." (PMID 32757036, 2020). "Its role in appetite and weight regulation was first postulated when it was observed that tumors overexpressing this hormone could induce cachexia in mice, which was ameliorated by an anti-GDF15 antibody." (PMID 32310257, 2020). "The recent discovery of GFRAL in the hindbrain may explain the role GDF15 in the loss of muscle mass noted in patients with COPD, probably mediated though cachexia, similar to cancer patients." (PMID 33344478, 2020). "Several studies have shown a direct correlation between serum GDF-15 levels and anorexia/cachexia." (PMID 32508832, 2020). "Moreover, the ability of PAR2 to control ALK5 protein abundance suggests the possibility that PAR2 can enhance the cellular actions of other TGF-β superfamily members, such as myostatin and GDF15, eventually leading to cancer-cachexia and muscle wasting." (PMID 27916875, 2016). "This study provides compelling evidence that targeting the GDF-15 pathway may offer a viable therapeutic strategy, while raising new mechanistic questions about how GDF-15 neutralization could be optimally integrated with other interventions to reverse the multifactorial cachexia syndrome." (PMID 42126170, 2026). "In conclusion, this study suggested circulating GDF15 is potentially suggestive of deterioration of the general condition, resulting from aging, organ dysfunction, and decreased muscle mass, which may lead to cachexia in EC patients." (PMID 41016991, 2026). "Our study shows that GDF-15 was associated with cachexia severity, was superior to standard CCa-associated biomarkers at classifying cachexia, and differentiated between non-cachexia and pre-cachexia status, but only among Hispanic/Latinx and non-Hispanic Whites." (PMID 39989973, 2025). "Thus, GDF15 represents a promising prognostic or predictive biomarker, and further prospective studies are required to validate its relevance related to different clinical conditions including pre-cachexia or cachexia." (PMID 40868185, 2025). "Therefore, our study supports the suggestion of GDF15 as a promising muscle wasting marker that may act as a biomarker for the early detection of cachexia and a potential therapeutic target in the clinical setting." (PMID 40558549, 2025). "In a phase 2 trial, visugromab, a humanized monoclonal antibody neutralizing GDF15, combined with nivolumab, demonstrated increased and durable responses in several heavily pretreated solid tumor cohorts and appeared to improve weight gain in patients with manifest cachexia." (PMID 40868185, 2025).